SLC7A11 (solute carrier family 7 member 11)
Diseases named in the same sentence as SLC7A11 in open-access papers (continued):
Sharing a sentence is not in itself a finding about the gene and the disease.
ovarian carcinoma (continued). "While the combined assessment of GPAT4 and SLC7A11 showed improved predictive ability compared with SLC7A11 alone, it was not as effective as using GPAT4 alone for predicting drug resistance in ovarian cancer." (PMID 40722736, 2025). "To evaluate the impact of the combined IHC score grouping of SLC7A11 and GPAT4 on the prognosis of ovarian cancer patients, we categorized the tissues that tested positive for both SLC7A11 and GPAT4 as the copositive group (n = 21)." (PMID 40722736, 2025). "Glucose deprivation induces disulfidptosis in SLC7A11high cells (high SLC7A11 expression), especially in cancers with a high DRG score, such as ovarian cancer." (PMID 40709550, 2025). "High expression of both SLC7A11 and GPAT4 was independently correlated with poor OS, highlighting the significance of this integrated metric as a prognostic factor in ovarian cancer." (PMID 40722736, 2025). "It has been found that the overexpression of Ets-1 in the human ovarian carcinoma cell line 2008 decreased intracellular ROS and increased intracellular GSH, GPX antioxidant activity, and SLC7A11 expression and activity." (PMID 38203758, 2024). "Interestingly, the studies discussed in this review also showed that SLC7A11 expression can be downregulated by natural (agrimonolide, fructose and eriodictyol) and synthetic (olaparib, lidocaine and erastin) compounds, suggesting a potential use of these compounds in ovarian cancer treatment." (PMID 38203758, 2024). "In addition, important cellular modulators, such as non-coding RNAs, Ets-1, CEBPG, ARID1A, SNAI2 and HRD1, could significantly regulate SLC7A11 expression in ovarian cancer cells, suggesting that these modulators could be potential therapeutic targets in ovarian cancer patients." (PMID 38203758, 2024). "PARP pharmacologic inhibition represents a major factor in treating ovarian cancer with mutations in the BRCA; inhibition of PARP enhances ferroptosis through suppressing SLC7A11 and synergizes with ferroptosis inducers within BRCA-proficient ovarian cancer." (PMID 38178187, 2024). "The results of cDNA expression profile analysis indicated that six genes, including GPX4, GSS, KEAP1, SQSTM1, SLC7A11, ATG3, and ATG5, were highly expressed in tumor tissues from patients with ovarian cancer." (PMID 37215446, 2023). "Some scholars have constructed a prognostic grading model of ovarian cancer containing 5 ferroptosis-related factors (ALOX12, ACACA, SLC7A11, FTH1, and CD44) through biological analysis, which showed great value in the prognostic analysis of this disease." (PMID 37304234, 2023). "PARP inhibition increases ferroptosis by inhibiting SLC7A11 and cooperates with ferroptosis inducers in BRCA-proficient ovarian cancer, while Nrf2 and STAT3 reduce ferroptosis by regulating SLC7A11, which alleviates IIR-ALI." (PMID 35805124, 2022). "Firstly, to identify the connection among SNAI2, ferroptosis and ovarian cancer, the expression level of SNAI2, SLC7A11 and GPX4 in human normal ovarian cell line IOSE-80 and multiple ovarian cancer cells were detected." (PMID 35220872, 2022). "Quantitative PCR analysis showed that SLC7A11 and GPX4 transcription were both upregulated in platinum‐resistant cell sublines compared with the parental ovarian cancer cell lines." (PMID 36485069, 2022). "Conversely, the inhibition of SLC7A11 and GPX4 decreased platinum resistance in ovarian cancer cells." (PMID 36485069, 2022). "It was reported that lidocaine was exhibited to promote ferroptosis and repress tumor growth of ovarian cancer by regulating miR-382-5p/SLC7A11 axis; PARP inhibition promoted ferroptosis in BRCA mutant ovarian cancer via repressing SLC7A11." (PMID 35220872, 2022).
ovarian carcinoma (continued). "SLC7A11 and GPX4 expression were both upregulated in platinum‐resistant cell sublines compared with their parental ovarian cancer cell lines, as determined via western blotting." (PMID 36485069, 2022). "Mechanistically, Radiotherapy suppressed the expression of SLC7A11 by activating the ataxia telangiectasia mutant gene (ATM), ultimately resulting in the accumulation of lipid peroxidation and ferroptosis in ovarian cancer cells." (PMID 36438923, 2022). "The aim was to assess the expression levels of SLC7A11 and GPX4 in relation to platinum resistance and prognosis in patients with epithelial ovarian cancer (EOC)." (PMID 36485069, 2022). "Inhibition of PARP1, an enzyme that can catalyze Poly(ADP-ribose) (PAR) formation, and plays a role in DNA damage repair, was recently shown to promote ferroptosis via repressing SLC7A11 and has a synergetic effect in BRCA-proficient ovarian cancer." (PMID 34445601, 2021). "Antisense lncRNA AS-SLC7A11 is significantly reduced in epithelial ovarian cancer (EOC) and has been proved to inhibit SLC7A11 expression in ovarian cancer." (PMID 33849550, 2021). "SLC7A11 interacts with SLC3A2 in the heterodimeric amino acid transport system x (c), which mediates cystine–glutamate exchange and maintains intracellular glutathione levels, resulting in cisplatin resistance in ovarian cancer cells." (PMID 40722736, 2025). "Our follow-up studies will continue to provide insights into the mechanisms by which GPAT4 regulates platinum resistance in ovarian cancer; we will increase the number of assessed patients with EOC and work to establish a link between SLC7A11 and the regulation of GPAT4." (PMID 40722736, 2025). "Continuously, our follow-up study will provide insights into the mechanisms by which GPAT4 regulates platinum resistance in ovarian cancer, adding prospective evaluation, increasing the number of patients with EOC, and establishing a link between SLC7A11 and the regulation of GPAT4." (PMID 40722736, 2025). "Furthermore, in comparison to the individual parameters (GPAT4 or SLC7A11 expression), a high co-expression level of GPAT4-SLC7A11 was identified as a more effective predictor of poor prognosis in ovarian cancer." (PMID 40722736, 2025). "al., showed that cultured and primary ovarian cancer cells lacking ARID1A expression have low SLC7A11, a downstream target of NRF2, resulting in specific vulnerability to inhibitors of the GSH metabolic pathway." (PMID 38358974, 2024). "Interestingly, CEBPG knockdown in A2780 and Hey ovarian cancer cells significantly decreased GPX4 and SLC7A11 expression." (PMID 38203758, 2024). "Moreover, expression levels of both SLC7A11 and GPX4 were upregulated in platinum-resistant A2780/DDP and SKOV3/DDP cells compared with the platinum-sensitive A2780 and SKOV3 parental ovarian cancer cells." (PMID 38203758, 2024). "Thus, SLC7A11 can modulate autophagy via ceRNA interactions with the autophagy genes STX17, RAB33B and UVRAG in ovarian cancer." (PMID 38203758, 2024). "Moreover, factors such as NADPH: quinone oxidoreductase 1 (NQO1) and Solute Carrier Family 7 Member 11 (SLC7A11, also known as xCT) increase the antioxidant defense of ovarian cancer cells, which is the primary reason for increased chemoresistance." (PMID 39710372, 2024). "In addition, lncRNA As-SLC7A11 levels were decreased in OVCA433, OVCA429 and TOV112D ovarian cancer cell lines compared with normal human ovarian surface epithelial (OSE) cells." (PMID 38203758, 2024). "Thus, agrimonolide acts as an apoptosis- and ferroptosis-inducing agent in ovarian cancer cells and induces ferroptosis through the modulation of the SCD1/SLC7A11/GPX4 axis." (PMID 38203758, 2024). "In ovarian cancer cells, treatment with the PARP inhibitor Olaparib can trigger ferroptotic death through the suppression of light chain subunit solute carrier family 7 member 11 (SLC7A11)-mediated GSH biosynthesis." (PMID 37163321, 2023).
ovarian carcinoma (continued). "Additionally, some scholars have identified and validated a novel ferroptosis-related gene signature, consisting of SLC7A11, ZFP36, and TTBK2, as an independent prognostic indicator for predicting the treatment response of ovarian cancer patients." (PMID 38028615, 2023). "The results of multiple gene correlation analyses indicated that there was a significant linear relationship (positive correlation) between the expression of ATF4 in ovarian cancer tissue and the expression levels of GPX4, GSS, KEAP1, NFE2L2, SLC7A11, ATG3, ATG4D, and ATG5." (PMID 37215446, 2023). "Specifically, the percentage of SLC7A11 high‐expression ovarian cancer tissues with a high GPX4 expression was 60.47% (26/43 cases), whereas it was only 12.08% (18/149 cases) in SLC7A11 low‐expression tissues; this difference was statistically significant (p < 0.001)." (PMID 36485069, 2022). "Considering the importance of SLC7A11 and GPX4 in ferroptosis, we speculated that SNAI2 might be involved in the regulation of ferroptosis, which accounted for its role in ovarian cancer." (PMID 35220872, 2022). "The results from qRT-PCR and Western blot assays showed that both the mRNA level and protein expression of SNAI2, SLC7A11 and GPX4 in SKOV3, A2780 and CAOV3 cells were higher than that in IOSE-80, suggesting that SNAI2, SLC7A11 and GPX4 were upregulated in ovarian cancer." (PMID 35220872, 2022). "So far, results indicate that SeChry induces cell death and xCT/SLC7A11 expression in both ovarian cancer cells and non-malignant cells." (PMID 31635026, 2019). "As a consequence of As-SLC7A11 overexpression, epithelial ovarian cancer cells were not able to use glutamate as AAs precursor or an energy source, inhibiting tumor growth." (PMID 31191327, 2019). "Additionally, our analyses revealed a negative correlation between KIF26B and SLC7A11 in ovarian cancer, particularly in chemoresistant tissues." (PMID 41751488, 2026). "To explore potential drugs targeting patients in the GMPI‐high group, we collected four ovarian cancer samples and calculated GMPI for each sample with the following formula: GMPI = 0.090* KIAA0100 + 0.043* ANKRD27 + 0.215* OPA3 + 0.171* NUMBL + 0.314* PDP1–0.233*SLC7A11–0.007* TRMT112." (PMID 38506093, 2024). "However, the link between SLC7A11 and GPX4 expression in platinum‐resistant ovarian cancer and its association with patient prognosis has not yet been reported." (PMID 36485069, 2022). "In addition to the classical SLC7A11 inhibitors (e.g., erastin and sorafenib), subsequent drug screening also found that regorafenib can inhibit SLC7A11, thereby enhancing the anticancer activity of PACMA31 in OVCAR-8 (human ovarian cancer cell line) cells in vitro and in vivo." (PMID 33842471, 2021). "Finally, we explored whether factors such as ATF4, GPX4, GSS, KEAP1, NFE2 like BZIP transcription factor 2 (NEF2L2), SLC7A11, SQSTM1, ATG3, ATG4D, and ATG5 have potential as non-invasive diagnostic markers for ovarian cancer." (PMID 37215446, 2023). "Furthermore, increased expression of SLC7A11, GPX4 or their upstream regulatory gene NRF2 not only promotes ferroptosis resistance, but is also correlated with a poorer prognosis and lower survival rate in many types of cancers, such as liver, lung and ovarian cancers." (PMID 35118067, 2021). "Most of ovarian cancer patients carry wild‐type BRCA with no significant clinical benefits from PARP inhibitors; however, recent studies have shown that this subset of patients is sensitive to targeted‐SLC7A11 ferroptosis inducers." (PMID 36485069, 2022).
colorectal cancer (76 papers, 2017 to 2026). A primary or metastatic malignant neoplasm that affects the colon or rectum. "Recent study reported that WTX deficiency inhibits ferroptosis in colorectal cancer cell hematogenous metastasis by inhibiting ubiquitination and degradation of SLC7A11 and FTL." (PMID 40109379, 2025). "CircSTIL is an increased circRNA in colorectal cancer, and its knockdown is associated with decreased proliferation and enhanced ferroptosis of colorectal cancer cells via the circSTIL/miR-431/SLC7A11 axis." (PMID 38778030, 2024). "Also, SLC7A11 expression was upregulated in breast and colorectal cancers, and was associated with unfavorable prognoses." (PMID 37087976, 2023). "In one study, 3,5-di-CQA was shown to suppress mitochondrial dysfunction and ferroptosis by regulating the expression of GPX4, ACSL4, and SLC7A11 in colorectal cancer cells." (PMID 39754271, 2025). "In particular, it is demonstrated that HPD regulates colorectal cancer ferroptosis by methylating SLC7A11/GPX4 through a moonlighting function." (PMID 41317403, 2025). "Erastin, a classic SLC7A11 inhibitor, was observed to induce intense cytotoxicity on colorectal cancer stem cells in vitro and in vivo and mitigated the chemoresistance of colorectal cancer stem cells." (PMID 39569390, 2025). "ALKBH5 reduces the transcriptional level of SLC7A11 by deleting m6A modification, thereby promoting ferroptosis in colorectal cancer." (PMID 39248438, 2024). "SLC7A11 expression is higher in oxaliplatin-resistant colorectal cancer cells compared to those sensitive to oxaliplatin." (PMID 39624080, 2024). "Talaroconvolutin A, a novel inducer of ferroptosis, effectively inhibited the growth of xenogeneic colorectal cancer cells by downregulating SLC7A11 and upregulating ALOXE3 in vivo experiments." (PMID 38082448, 2023). "Targeting SLC7A11 specifically suppresses the progression of colorectal cancer stem cells by inducing ferroptosis." (PMID 37238692, 2023). "SLC7A11 attracted our attention as it is identified as the substrate of OTUB1 in other tumors and targeting SLC7A11 indeed can specifically kill CSCs in colorectal cancer." (PMID 34927544, 2021). "Interestingly, vitamin D or 2-imino-6-methoxy-2H-chromene-3-carbothioamide was observed to down-regulate SLC7A11 expression to inhibit colorectal cancer growth through induction of ferroptosis." (PMID 39569390, 2025). "Additionally, another research also suggested that NaB promoted ferroptosis in colorectal cancer cells through the CD44/SLC7A11 pathway." (PMID 38397738, 2024). "It is probably due to that just blocking SLC7A11 cannot eliminate intracellular cysteine efficiently, whereas blocking both cysteine and cystine import might induce ferroptosis more effectively in colorectal cancer cells." (PMID 39079386, 2024). "By down-regulating the expression of SLC7A11, inhibiting the activity of System Xc−, reducing the content of cysteine and glutathione, leading to the accumulation of reactive oxygen species and inducing ferroptosis in colorectal cancer cells." (PMID 37580745, 2023). "For example, lncRNA FLVCR1-AS1 mediates the miR-23a-5p/SLC7A11 axis to promote malignant behavior in cervical cancer cells; The downregulation of lncRNA SLC7A11-AS1 reduced the expression of NRF2/SLC7A11 and inhibited the progression of colorectal cancer cells." (PMID 38097686, 2023). "TCGA and GTEx data revealed high GPX4 and SLC7A11 expression in colorectal cancer." (PMID 35978266, 2022). "Next, we analyzed the link between YY2 and SLC7A11 in clinical colorectal cancer tissues." (PMID 35246964, 2022). "For example, the progression of colorectal cancer stem cells could be specifically suppressed upon targeting SLC7A11, followed by inducing ferroptosis." (PMID 34531924, 2021). "In addition, SLC7A11 expression was reported to have a positive correlation with clinical data including lymph node metastasis status and disease recurrence status in tissues of colorectal cancer patients." (PMID 39335604, 2024).
colorectal cancer (continued). "Studies have reported that elastin, a ferroptosis inducer, could irreversibly inhibit SLC7A11 and synergize with cisplatin to increase the drug’s cytotoxicity, and that the blocking of SLC7A11 effectively increased the intracellular level and cytotoxicity of cisplatin in colorectal cancer." (PMID 34790572, 2021). "For example, 2-imino-6-methoxy-2H-chromene-3-carbothioamide (IMCA) reduces the expression of SLC7A11 and depletes cysteine and GSH, which decreases the activity of colorectal cancer cells in vitro and inhibits tumor growth in vivo." (PMID 40721409, 2025). "The transcription of SLC7A11, SLC3A2, SLC1A4, and SLC1A5 in colorectal cancer cells were all activated under hypoxia condition." (PMID 39079386, 2024). "In colorectal cancer, AADAC reduces lipid peroxidation by scavenging ROS in a SLC7A11-dependent manner, thereby protecting metastatic CRC cells from undergoing ferroptosis." (PMID 36743693, 2023). "Additionally, pharmacological inhibition of JNK with SP600125 partially reversed the β-lapachone-induced decrease in SLC7A11 and GPX4 expression levels in colorectal cancer cells." (PMID 40375133, 2025). "Furthermore, expression of glutaminolysis-related genes GLS, SLC7A11 and SLC1A5 were significantly decreased in the colorectal carcinoma cells treated with low-dose PTX." (PMID 28522974, 2017).